LEP (leptin)
Diseases named in the same sentence as LEP in open-access papers (continued):
Sharing a sentence is not in itself a finding about the gene and the disease.
Arthritis (continued). "SLE patients without fever, rash, arthritis, serositis, hematologic disorders, and active nephritis exerted higher serum leptin levels." (PMID 37006245, 2023). "On the other hand, in the proliferative arthritis model of zymosan-induced arthritis (ZIA), leptin appears to have a different function, as histopathology showed that ob/ob mice and mice with leptin receptor deficiency (db/db) had delayed arthritis resolution and more joint damage than controls." (PMID 38001998, 2023). "Experiments carried out in rodents lacking leptin expression or leptin receptors showed that these animals have less antigen induced arthritis ability, proving that leptin signalling increases synovial inflammation." (PMID 33673730, 2021). "Also, Leptin was found significantly reduced in the plasma of CIA and CIA+FD animals, but its role in arthritis is still controversial." (PMID 31683648, 2019). "Thus, smoking-induced low levels of IGF1 and leptin may support the aberrant T-cell formation at the preclinical stage of arthritis, in the poor bone remodelling and progressive joint damage in the overt arthritis, and for the early cardiovascular mortality in RA." (PMID 27041823, 2016). "Their results showed higher leptin levels in subjects with arthritis and MetS than arthritis patients without MetS." (PMID 24741591, 2014). "It has been demonstrated that leptin mutant mice, although obese, do not develop OA, thereby strongly suggesting that leptin is required for the development of arthritis in obese mice." (PMID 22745906, 2012). "Fenofibrate treatment prevented the inhibitory effect of arthritis on serum leptin, whereas in control rats, fenofibrate did not modify serum concentration of leptin." (PMID 23781298, 2012). "As previously reported, arthritis induced a marked decrease in serum concentrations of adiponectin and leptin, whilst serum resistin was not significantly decreased." (PMID 23781298, 2012). "In contrast to serum adiponectin and leptin concentrations, arthritis, fenofibrate treatment, or pair-feeding the rats did not change serum concentration of resistin." (PMID 23781298, 2012). "Arthritis decreased serum leptin, adiponectin, and insulin (P<0.01) but not resistin levels." (PMID 23781298, 2012).
endometriosis (42 papers, 2011 to 2026). The growth of functional endometrial tissue in anatomic sites outside the uterine body. "Endometriosis pain is associated with inflammatory cytokines, such as leptin (LEP), through activation with its receptor (LEPR), and its expression can be influenced by the presence of genetic polymorphisms." (PMID 40673025, 2025). "Leptin, a hormone linked to inflammation and energy metabolism, has also been extensively studied in the context of endometriosis." (PMID 39595927, 2024). "High levels of peritoneal fluid leptin have been consistently associated with endometriosis in humans." (PMID 36140261, 2022). "Understanding the changes in body weight as a phenomenon caused by metabolic disruption of leptin signaling and development of endometriosis resolves this conundrum." (PMID 36140261, 2022). "Leptin, secreted by adipocytes, has been associated with angiogenesis and inflammation in endometriosis with circulating levels in patients found to be high or unchanged which seems to depend upon the location and severity of the disease." (PMID 36284640, 2021). "The interest in the understanding of the association between leptin and endometriosis has been increasing." (PMID 26242176, 2015). "Leptin, a hormone that is mainly produced by adipocytes, is also expressed in endometrium and has been implicated in endometriosis." (PMID 26242176, 2015). "The present data suggest that serum leptin/BMI ratio is associated with the presence of endometriosis." (PMID 23634146, 2013). "Notably, modulators of eating behavior, such as leptin, endocannabinoids, and dopamine, have also been implicated in aspects of the pathophysiology of endometriosis." (PMID 41563503, 2026). "Additionally, more comprehensive data regarding leptin as a diagnostic biomarker are necessary for a clearer understanding of its potential utility in the diagnostic process of endometriosis." (PMID 38567305, 2024). "Furthermore, elevated levels of leptin have been linked to endometriosis and disrupted trophoblast invasion, through defects on ECM remodelling." (PMID 39090270, 2024). "Further studies are needed to delve into the underlying mechanisms through which leptin operates in endometriosis, determining whether observed changes in leptin concentrations contribute to or are the result from the disease’s pathogenesis." (PMID 38567305, 2024). "Understanding this association between leptin, diet, and endometriosis may provide clues for clinicians on how to advise these patients and develop new strategies for this treatment-refractory and debilitating disease." (PMID 36140261, 2022). "However, obese recipient mice with leptin deficiency and leptin receptor deficiency showed suppressed endometriosis development compared with control mice." (PMID 36140261, 2022). "Furthermore, donor uterine tissues with leptin deficiency and leptin receptor deficiency suppressed endometriosis development compared with control donor in control recipient mice." (PMID 36140261, 2022). "Leptin is known to reflect adiposity, and as paradoxical as it may seem, there is an inverse relationship between BMI and the risk of endometriosis." (PMID 36140261, 2022). "MicroRNA alterations associated with endometriosis affect genes such as Cebpa, Cebpb, and Ppar-γ, which are involved in brown adipocyte differentiation, leptin and adipoq, which are involved in glucose metabolism, and IL-6 and HSL, which are involved in fat metabolism." (PMID 30982470, 2019). "About breaking peritoneal fluid homeostasis, there is evidence that leptin and 6-keto-prostaglandin F1 alpha (6-KF) are significantly elevated in peritoneal fluid of women with endometriosis, and this may play a role in endometriosis-associated pain." (PMID 23671540, 2013). "Thus, findings from the present study may provide further insight into leptin’s part in the inverse association of low BMI and endometriosis." (PMID 36140261, 2022).
endometriosis (continued). "Moreover, the possibility of an association between the PF leptin levels and severity of endometriosis is also controversial; some studies have suggested a negative correlation, while others have shown a positive correlation with more severe forms of peritoneal endometriosis." (PMID 26242176, 2015). "Thus, peritoneal disease, but not ovarian endometriotic cysts, influences the concentration of leptin in PF in endometriosis; these two types of endometrial lesions may have different pathogenic mechanisms and distinct leptin-biosynthetic capacities." (PMID 24401660, 2014). "Moreover, the possibility of an association between PF leptin levels and severity of endometriosis is also controversial, with some studies suggesting a negative correlation and others showing a positive correlation with more severe forms of peritoneal endometriosis." (PMID 23634146, 2013). "A recent study reported increased plasma leptin levels, and a systematic review reported an elevated leptin-to-BMI ratio in women with endometriosis, with significantly lower leptin levels in advanced stages." (PMID 41563503, 2026). "Adipose-derived hormones and cytokines (e.g., leptin) promote systemic inflammation and angiogenesis in endometriosis." (PMID 40565786, 2025). "More recently, molecule such as leptin, which is known to regulate long-term energy balance, has been evaluated as a potential biomarker for endometriosis." (PMID 38567305, 2024). "The mean plasma leptin concentration (ng/mL) were comparable in two groups, 15.578 ± 5.162 ng/mL in women with endometriosis, and 15.530 ± 6.404 ng/mL in the control group." (PMID 38567305, 2024). "Worth to note is that, a positive and statistically significant correlation of moderate strength was observed between the concentration of leptin in peritoneal fluid and plasma within the endometriosis group." (PMID 38567305, 2024). "The contrast analysis revealed statistically significant differences in trends (quadratic polynomial) between the endometriosis group and the control group, both in the distribution of mean leptin/BMI ratio in plasma and in PF." (PMID 38567305, 2024). "The aim of this study was to analyze the concentration of leptin in peritoneal fluid and plasma and to assess their role as potential biomarkers in the diagnosis of endometriosis." (PMID 38567305, 2024). "The aim of this study was to compare leptin/BMI ratio in biological fluids (plasma and peritoneal fluid) between women diagnosed with endometriosis and a control group, using SPRi biosensors." (PMID 38567305, 2024). "Although findings are somewhat ambiguous, most research suggests that leptin concentrations are elevated in both peritoneal and follicular fluid of women with endometriosis compared to controls." (PMID 39595927, 2024). "Other studies have reported increased leptin levels in migraine, pelvic pain in endometriosis, lipedema, low back pain, and multisomatoform disorder (MSD)." (PMID 37559026, 2023). "Our results contradict previous studies that showed significantly higher leptin levels in peritoneal fluid than in plasma of women with endometriosis and higher levels of leptin in endometrial tissues." (PMID 38075048, 2023). "Endometrial tissues of 44 women with endometriosis were further shown to express higher levels of leptin and leptin-receptor protein than tissues obtained from 42 non-affected women." (PMID 36289764, 2022). "To investigate leptin’s contribution to the pathogenesis of endometriosis, we designed and demonstrated how decreased leptin signaling negatively impacts the induction of endometriosis in a mouse model." (PMID 36140261, 2022). "Increased levels of leptin in serum and peritoneal fluid specimens from women with endometriosis consistently have been reported since 2000." (PMID 36140261, 2022). "Uncovering the pathophysiology of leptin signaling in endometriosis requires easy assays to distinguish endometriotic lesions from surrounding normal tissues." (PMID 36140261, 2022).
endometriosis (continued). "This analysis also observed that leptin declined in patients with advanced-stage disease in comparison to patients with early endometriosis." (PMID 36289764, 2022). "Our results from the ob/ob and db/db mice suggest a critical role of leptin signaling in endometriosis develpment." (PMID 36140261, 2022). "This explains the elevated levels of leptin observed in earlier stages of endometriosis compared with more advanced stages of disease." (PMID 36140261, 2022). "It was also suggested that microRNAs, which differ in the serum of patients with endometriosis and controls, altered the leptin levels released by fat tissues." (PMID 36289764, 2022). "Our study demonstrates that an aberrant higher level of leptin stimulates endometriosis development in mice with normal body weight." (PMID 36140261, 2022). "Two meta-analysis provided further evidence for higher leptin concentrations in the peritoneal fluid of women with endometriosis compared to the respective controls." (PMID 36289764, 2022). "In a previous study, it was demonstrated that the disruption of leptin signaling by the injection of a pegylated leptin peptide receptor antagonist impairs the establishment of endometriosis-like lesions." (PMID 36140261, 2022). "Leptin’s role in the development of endometriosis is not clearly understood, but increased levels of leptin in peritoneal fluid of endometriosis patients have been consistently reported." (PMID 36140261, 2022). "A meta-analysis published in 2021 also showed higher leptin levels in the serum of women with endometriosis." (PMID 36289764, 2022). "Our results suggest that leptin in ectopic lesions and body plays a critical role in endometriosis development." (PMID 36140261, 2022). "In summary, we demonstrate the role of leptin and leptin signaling in the pathogenesis of endometriosis in an experimental mouse model." (PMID 36140261, 2022). "Experimental studies reported leptin to significantly enhance the proliferation of both eutopic and ectopic endometrial stromal cells in endometriosis." (PMID 36289764, 2022). "Leptin, a product of the obese (ob) gene, was shown to be markedly elevated in the serum and PF of patients with endometriosis, and it has been reported that the expression of leptin and its receptor increases in ovarian endometriomas." (PMID 34072419, 2021). "We observed increased mesenteric fat and serum leptin levels in the endometriosis animals that were decreased by exercise." (PMID 36284640, 2021). "Increased levels of leptin have been identified in serum and peritoneal fluid specimens from women with endometriosis for more than two decades." (PMID 33986637, 2021). "The result matches our study in relation to increase in the serum leptin level significantly in the patient with endometriosis, but our study revealed that there was a direct significant relation with the severity." (PMID 32963544, 2020). "Blood sample was taken from all patients in the theater room when laparoscopy finding went with endometriosis, and classifying according to surgical staging of endometriosis, the level of serum leptin was measured by ELISA using Human LEP (Leptin) ELISA Kit." (PMID 32963544, 2020). "Gene expression analysis showed that endometriosis altered the expression of Cebpa, Cebpb, Ppar-γ, leptin, adiponectin, IL-6, and HSL, which are involved in driving brown adipocyte differentiation, appetite, insulin sensitivity and fat metabolism." (PMID 30982470, 2019). "All of these variables are responsible for the controversy in the literature, which makes the role of leptin in the pathology of endometriosis an enigma." (PMID 26242176, 2015). "Considering all fifteen patients, the peritoneal endometriosis group presented with significantly high serum leptin levels compared to the control group (control = 14.7 ± 2.63, endometriosis = 19.25 ± 1.84, ng/mL, p < 0.0001)." (PMID 26242176, 2015).
endometriosis (continued). "In this study, we showed that endometriosis patients presented with high levels of serum leptin, while the peritoneal fluid levels were unchanged compared to the control ones." (PMID 26242176, 2015). "Together with data from literature, these data suggest that the presence of peritoneal disease, and not of an ovarian implant, is the factor that influences the concentration of leptin in the serum and PF in endometriosis." (PMID 26242176, 2015). "Based on these results and the fact that estrogen positively regulates leptin, the endometriosis group should have normal serum and low PF leptin levels." (PMID 26242176, 2015). "Recently we have published a study on endometriosis stage IV patients in which we found that that leptin levels in both the serum and PF were changed." (PMID 26242176, 2015). "A recent report demonstrated that leptin signaling is a necessary component of lesion proliferation, early vascular recruitment, and the maintenance of neoangiogenesis in a murine model of endometriosis." (PMID 24401660, 2014). "Due to its inflammatory and angiogenic properties, as well as its possible involvement in reproductive abnormalities at both the central and the gonadal levels, leptin has been extensively studied in patients with endometriosis." (PMID 24401660, 2014). "A negative and significant correlation was found between OB-RL mRNA expression and peritoneal fluid leptin/BMI ratio only in endometriosis." (PMID 23634146, 2013). "A positive, significant correlation was observed between leptin and OB-RL transcripts in ectopic endometria and also in eutopic endometria in endometriosis and control groups." (PMID 23634146, 2013). "A trend toward significantly higher PF leptin/BMI ratio was also observed in the endometriosis group (P = 0.07)." (PMID 23634146, 2013). "Nevertheless, the clinical applicability of the leptin/BMI ratio for prediction of endometriosis still requires confirmation." (PMID 23634146, 2013). "Despite the strong relationship between leptin and BMI, only a few studies have analyzed the leptin/BMI ratio instead of leptin concentrations in women with endometriosis." (PMID 23634146, 2013). "In the present study, we found a trend toward higher levels PF leptin/BMI ratio in the presence of endometriosis." (PMID 23634146, 2013). "The paper entitled “Gene expression of leptin and long leptin receptor isoform in endometriosis: a case-control study” is an original clinical study suggesting a putative role of leptin in the development of endometrial implants." (PMID 24379834, 2013). "Leptin is thought to play a role in endometriosis through its inflammatory and angiogenic properties." (PMID 23634146, 2013). "Some investigators have also reported higher PF leptin in women with endometriosis as compared to controls." (PMID 23634146, 2013). "We observed that expression of leptin and OB-RL transcripts was significantly higher in ectopic versus eutopic endometrium of patients with endometriosis and normal pelvis controls." (PMID 23634146, 2013). "Therefore, this study aims to evaluate the role of the LEP rs7799039 and LEPR rs1137100 polymorphisms in the painful symptoms of endometriosis in Brazilian women." (PMID 40673025, 2025). "Leptin levels also correlated positively with the endometriosis stage." (PMID 41009445, 2025). "The authors concluded that leptin and its receptor are critical for endometriosis development." (PMID 38933332, 2024). "Additionally, through the assessment of both leptin concentrations in plasma and peritoneal fluid, we investigated their interrelationships and potential impact on the pathogenesis of endometriosis." (PMID 38567305, 2024). "Notably, within the primary infertility subgroup, the level of leptin/BMI in PF was significantly lower in the endometriosis group compared to the control group." (PMID 38567305, 2024). "Leptin/BMI ratio according to the stage of endometriosis, endometrioma and cycle phase." (PMID 38567305, 2024).